EGFR (epidermal growth factor receptor)
Diseases named in the same sentence as EGFR in open-access papers (continued):
Sharing a sentence is not in itself a finding about the gene and the disease.
tumor (continued). "Secreted BICA generated an effective immune response and reduced tumor growth in epidermal growth factor receptor (EGFR)/major histocompatibility complex-related chain A (MICA)-positive tumors in vitro." (PMID 40741595, 2025). "As highlighted, the EGFR/MAPK signaling pathway is closely associated with oncogenic processes, making it significant in driving tumor growth and the progression of CRC." (PMID 40149618, 2025). "Using TNBC as the tumor model, we characterized the role of EGFR in sensitizing cancer cells to CAP treatment." (PMID 39781456, 2025). "Amplification and polysomy, although distinct genetic events, both lead to EGFR protein overexpression, activating downstream signalling pathways that promote tumour growth and survival." (PMID 40149368, 2025). "CAR-T cell therapies directed against HER2, mesothelin and EGFR are also under investigation in thoracic tumors; however, on-target/off-tumor toxicities, limited trafficking into solid tumor sites, and the highly immunosuppressive TME remain major obstacles." (PMID 41472727, 2025). "These processes are regulated by oncogenic alterations such as EGFR amplification, PTEN loss, and HIF-1α stabilization, which allow tumor cells to thrive in hypoxic and nutrient-poor environments." (PMID 41450919, 2025). "Gefitinib inhibits EGFR tyrosine kinase activity, suppressing tumor cell proliferation, invasion, and metastasis while promoting apoptosis, which is relevant given EGFR overexpression in GC80." (PMID 40281132, 2025). "One mechanism is by inducing IL-6 trans-signalling by shedding sIL-6R, a process particularly important in KRas-mutant cancers, where it promotes tumour growth and progression, contributing to resistance against EGFR-targeted therapies." (PMID 40427200, 2025). "We also identified cg02316066 positively (r = .53), while cg14344486 and cg18809076 negatively (r = −.79 and r = −.54, respectively), correlated to EGFR expression, highlighting potential targets for tumour progression driven by high EGFR expression." (PMID 41292185, 2025). "The role of EUDAL in shaping the tumor cell response to hypoxia-induced EGFR activation was also elucidated." (PMID 40940319, 2025). "This leads to a starker separation between EGFR-mutant and KRAS-mutant tumours, while also highlighting the association of other events such as STK11 mutation in the determination of which evolutionary trajectory a tumour will follow." (PMID 41509216, 2025). "The right temporal lobe tumor exhibited EGFR amplification and homozygous deletion of CDKN2A/B, and genetic changes have often been linked to more aggressive tumor behavior." (PMID 41473634, 2025). "In our series, p-EGFR expression in tumor specimens and cervical nodes was comparable, with a TPS of ≥1% in 21% of patients." (PMID 40738059, 2025). "Our in vitro and in vivo results showed that hypoxic tumor cells with high levels of EGFR activation and autophagy were more resistant to chemotherapy than those with low levels of activated EGFR or autophagy." (PMID 40940319, 2025). "It has been found that the up-regulation of lncRNA NEAT1 can increase the expression of Bcl-2 and EGFR, thus promoting the proliferation and invasion of tumor cells." (PMID 41186893, 2025). "Pathologically, EGFR contributes to cancers due to its key role in uncontrolled tumor proliferation." (PMID 41465166, 2025). "Meanwhile, FH-EB02 is a promising B7H3/EGFR bsAb with significant anti-tumor activity and tolerable toxicities, which warrants further clinical investigation." (PMID 41291854, 2025). "The direct tumor inhibition effect by EGFR/c-MET signaling blockade was presented in xenograft efficacy models of the benchmark molecule amivantamab." (PMID 39995668, 2025). "Upregulated CTHRC1 enhances tumor invasion and migration via the EGFR/ERK1/2/AKT pathway and also influences immune response and angiogenesis." (PMID 40136652, 2025).
tumor (continued). "Dose-dependent cell lysis was observed in B7H3 and EGFR co-expressing tumor cells NCI-H1975 when treated with the four bsAbs." (PMID 41291854, 2025). "The most prevalent mutation, EGFR variant III (EGFRvIII), is a constitutively active form of the receptor, which is associated with enhanced tumor aggressiveness and a worse prognosis for GB patients." (PMID 40191718, 2025). "In the reported studies, the most frequently measured clinical outcomes were survival rates and tumor recurrence, with additional studies on therapeutic effectiveness with therapies targeting biomarkers such as EGFR and HRAS." (PMID 41465166, 2025). "Among patients with mutant EGFR, carriers of the ADAM9 rs6474526 G allele (TG + GG) demonstrated a significantly increased risk of larger tumor sizes (OR = 2.939, 95% CI = 1.099–7.858; p = 0.025)." (PMID 40429751, 2025). "In solid tumours, GE11 peptide modified exosomes successfully delivered let-7a miRNA to epidermal growth factor receptor positive breast cancer cells, restoring tumour-suppressor miRNA levels and reducing proliferation in vitro and in vivo." (PMID 41181109, 2025). "Results show improved delivery of siRNA and inhibition of metastasis and tumor growth by silencing the EGFR (epidermal growth factor receptor) gene." (PMID 41471830, 2025). "Analyses of biopsies before and after treatment with BsAbs targeting EGFR (amivantamab) or HER2 (zintokalimab) have demonstrated substantial intercellular variation in antigen density within single tumor niches." (PMID 41262250, 2025). "Despite its proposed role as an EGFR‐dependent tumor suppressor, the functional consequences and clinical relevance in cancer etiology remain incompletely understood." (PMID 39129344, 2025). "The nuclear EGFR plays a co-transcriptional regulatory role that promotes treatment resistance and tumor aggressiveness." (PMID 41283264, 2025). "Radiotherapy-induced AREG targeted EGFR+ MNPs in the metastatic microenvironment, induced anti-inflammatory transcriptomic state in MNPs, and promoted phagocytosis resistance of tumor cells by increasing ‘don’t-eat-me’ CD47 signal." (PMID 40725192, 2025). "From this perspective, KRAS-and EGFR-mutant tumors obviously diverge at multiple points in anti-tumor response, leading to distinct immune microenvironment phenotypes." (PMID 40809430, 2025). "In this study, we performed genomic and transcriptomic analyses of EGFR-mutated NSCLC tumor and cell lines to evaluate the relationship between CIN and the effect of EGFR-TKIs as well as the activity of the intrinsic cGAS–STING signaling pathway." (PMID 40136696, 2025). "Oncogenic mutations, including EGFR variant III (EGFRvIII), which seems to be expressed only in tumor tissue, are the specific target of some immunotherapies." (PMID 40236691, 2025). "A recently published paper highlighted that radiotherapy increased AREG expression in tumor tissues, which induced distant metastasis growth by reprogramming EGFR+ mononuclear phagocytes (MNPs) into an immunosuppressive phenotype." (PMID 40725192, 2025). "Research indicates that resveratrol can enhance the sensitivity of cancer cells to the effects of EGFR-targeted therapies by influencing tumor microenvironment factors and cytokine signaling pathways." (PMID 40732249, 2025). "All 4 radioimmunoconjugates demonstrated strong EGFR-specific targeting, with increasing tumor uptake over 15 d and reduced uptake on blocking." (PMID 40639908, 2025). "Despite these challenges, the integration of EGFR inhibitors with other targeted therapies holds promise for addressing the complex tumor microenvironment in RCC." (PMID 40677703, 2025). "Whereas interactions necessary of T‐cell activation, like MIF (interacting with CXCR4, CD74 and CD44), PPIA (interacting with BSG) and CXCL16 (interacting with CXCR6 on CD8+ T‐cells) were down‐regulated in high EGFR expressing tumour cells." (PMID 40621643, 2025).
tumor (continued). "None of the included NSCLC patients bared targetable genetic tumor alterations (EGFR, ALK, or ROS1)." (PMID 40091413, 2025). "Our study reflects this issue, as anti-EGFR monotherapy was found to elevate pro-tumor markers, underscoring the limitations of single-agent therapies." (PMID 40191718, 2025). "We then used the epidermal growth factor receptor (EGFR), a well-studied target protein renowned for its substantial implications in tumor growth and metastasis, to evaluate the model’s application in word generation." (PMID 41375113, 2025). "The overexpression or amplification of HER2 further facilitates aggressive tumor behavior, while the EGFR activation enhances tumor proliferation and survival." (PMID 40563418, 2025). "Several cancer therapies consist of antibodies that engage CD16a to trigger cellular immunity, such as cetuximab that binds and blocks epidermal growth factor receptor (EGFR) in tumor cells and induces ADCC2." (PMID 41219228, 2025). "Another study of 106 tumour sections also revealed that nearly all tumours expressed EGFR, with high expression levels being observed in 78% of cases." (PMID 40426729, 2025). "Developing bispecific antibodies that combine anti-SIRPα mAbs with tumor opsonizing mAbs, such as anti-EGFR, represents a promising approach." (PMID 40136470, 2025). "Still, entinostat specific properties cannot explain these divergent findings since the same drug was also capable of EGFR downregulation, albeit in a non-tumor context." (PMID 39864337, 2025). "By utilizing scRNA-seq, researchers can monitor the dynamic changes in tumor cells during EGFR-TKI treatment." (PMID 40003951, 2025). "The pivotal role of MIG6 segment 1/2 domains and phosphorylation at Y394/Y395 residues in the tumor suppressing activity of MIG6 was further explored through an in vitro kinase assay utilizing purified EGFR L858R mutant and MIG6 GST fusion proteins." (PMID 39129344, 2025). "Our study found a reduced maturation of tumor‐infiltrating DCs in EGFR mutant LUAD compared to EGFR wild‐type LUAD." (PMID 40130724, 2025). "For example, in clinical practice, patients with EGFR-mutant NSCLC have shown substantial tumor shrinkage after neoadjuvant EGFR inhibition, facilitating less extensive surgical resections." (PMID 39796742, 2025). "As a result, it effectively inhibits tumor cells that express both EGFR and HER3, minimizing the effect on functioning HER3 in normal tissues." (PMID 40510353, 2025). "Anti-EGFR CAR-T cells exhibited specific cytolytic activity against EGFR-positive tumor cells in vitro and in mice." (PMID 39859299, 2025). "Antagonistic effects such as inhibition of EGF-dependent receptor phosphorylation, cell proliferation and tumor growth have been described for various EGFR-specific biparatopic molecules." (PMID 40536585, 2025). "For example, the IgTT-4E1-S antibody, targeting PD-L1, EGFR, and 4-1BB, enables selective PD-L1 blockade and conditional 4-1BB activation in EGFR+ tumor cells." (PMID 41262250, 2025). "The expression of EGFR on circulating tumor cells (CTCs) in the peripheral blood of patients undergoing radical resection for NSCLC has been reported." (PMID 41373464, 2025). "This study provides novel insights into EGFR‐amplification mediated immune suppression in oral tumours, which was present in 22.22% of tumours from female OSCC patients." (PMID 40621643, 2025). "It has been demonstrated that H1-MPA exhibits high EGFR affinity, low cytotoxicity, strong tumor uptake, and a high tumor-to-background ratio (TBR)." (PMID 40906195, 2025). "Genetic ablation of TMED2 was previously shown to induce the degradation of EGFR, therefore resulting in an anti-tumor effect." (PMID 40497947, 2025).
tumor (continued). "These concepts warrant further investigation in ESCC, particularly considering the poor outcome of these patients and the unsuitability of EGFR-positive tumours for treatment with immune checkpoint inhibitors." (PMID 40615716, 2025). "High expression of EUDAL facilitates sustained phosphorylation of EGFR in hypoxic tumor cells and subsequently activates downstream STAT3/BNIP3 signaling, which leads to autophagy-related drug resistance." (PMID 40940319, 2025). "The two antibody-conjugated fluorescent-SERS dots (F-SERS dots) targeted EGFR tumor markers within tumor cells and tumor-secreted VEGF in the tumor microenvironment." (PMID 39934124, 2025). "For instance, early‐stage EGFR mutant tumours display more complete epithelial characteristics compared with KRAS mutant tumours." (PMID 40847555, 2025). "In particular, its interaction with EGFR enhances receptor activation, thereby promoting tumor progression." (PMID 41035668, 2025). "Remarkably, for other tumor entities mainly inhibitory effects of HDACi on EGFR expression have been described, and their influence on ligands of EGFR is generally under-investigated so far." (PMID 39864337, 2025). "Our group’s work on recombinant immunotoxins targeting overexpressed EGFR has also shown anti-tumor efficacy in HNSCC." (PMID 39859304, 2025). "Following 72 h, enhancement of tumor formation was appraised in human MSCs (hAMSCs)-treated HT-29 cells by EGFR/c-Src/IRSp53/p-AKT/p-Stat3 signal network employing qRT-PCR, besides the Western blot technique, as well as the MTT and hanging drop assays." (PMID 41200137, 2025). "In our research, the expression of ZEB2 was increased in both EGFR-TKI-resistant NSCLC tumor cells and EGFR-TKI-resistant patients’ samples." (PMID 40510028, 2025). "EGFR is a receptor tyrosine kinase that drives tumour progression and upregulates the TME by activating downstream oncogenic kinases and transcription factors." (PMID 40830825, 2025). "The marked reduction in tumor spheroid size observed following mitoxantrone treatment in both EGFR- and TLR-stimulated conditions strongly suggests that USP11 is a promising therapeutic target for EGFR- or TLR-driven CRC." (PMID 41419456, 2025). "Intracranial NSCLC tumor tissues from vehicle or osimertinib treated mice were extracted and analyzed for activation of exon 19 deleted EGFR and downstream kinase activity." (PMID 40051661, 2025). "Frequent EGFR amplifications and TERT gene promoter mutations lead to the deregulation of tumor cell proliferation and increased aggressiveness." (PMID 41465586, 2025). "We integrate multiple scRNA‐seq datasets to identify cell subclusters most relevant to tumor stage, patient survival, and EGFR–TKIs response." (PMID 40162549, 2025). "Cetuximab-IRDye800CW provides stable, tumor-specific, high-contrast fluorescence imaging in EGFR-high CRC models." (PMID 41346398, 2025). "In conclusion, DNAJC10 inhibits GBM migration, invasion, and tumor propagation in vitro and in vivo by targeting EGFR." (PMID 41191192, 2025). "The tumor retained the EGFR exon 19 deletion and showed an acquired MET amplification at progression." (PMID 41226501, 2025). "Preclinical investigations have demonstrated that siRNAs directed against EGFR or anti-apoptotic genes such as Bcl-2 can significantly suppress tumor progression and even restore sensitivity to chemotherapy agents such as taxol." (PMID 41304872, 2025). "The distribution pattern of intravenously injected Pan‐IR700 overlapped that of tumor cells, as visualized by EGFR immunofluorescence staining, and overlapped that of EGFR immunofluorescence staining." (PMID 40830817, 2025). "This localized secretion enhances BiTE concentration at the tumor, enabling precise activation of T cells via CD3 binding and simultaneous targeting of tumor-associated antigens (TAAs) like HER2 or EGFR." (PMID 39982231, 2025).
tumor (continued). "Emerging evidence suggests that somatic mutations in driver genes can modulate tumor immunogenicity; for example, ALK rearrangements, EGFR mutations, and KRAS mutations correlate with immunosuppressive tumor microenvironments (TMEs)." (PMID 40873541, 2025). "Exosomes released into circulation possess the potential to provide insights into tumor status, as evidenced by the correlation between plasma exosomal microRNAs and the efficacy of immunotherapy in EGFR/ALK wild-type advanced NSCLC." (PMID 41573685, 2025). "This ADC efficiently released oxaliplatin, inhibited tumour cell proliferation, and exhibited enhanced accumulation in tumour models with high EGFR expression in vivo." (PMID 40518502, 2025). "The improvement in the delivery of LNP due to utilizing the EGFR antibodies as targeting moieties resulted in an increased level of gene editing in tumor cells mediated by CRISPR‐Cas9." (PMID 39736115, 2025). "Next-generation ADCs with dual targeting capabilities (e.g., ZW49 targeting HER2/EGFR) address tumor heterogeneity and resistance." (PMID 41184856, 2025). "Off-tumor toxicity remains a significant concern, particularly for EGFR-targeted approaches where careful monitoring of normal tissue expression is essential." (PMID 41348261, 2025). "Single-cell sequencing further reveals that EGFR-independent clones in the tumor microenvironment propagate resistance via exosomal miRNAs, underscoring the need to target the tumor ecosystem in TKI-resistant cells." (PMID 41381443, 2025). "NF‐κB, as an oncogenic transcription factor, plays a significant role in the control of tumour progression and the microenvironment by EGFR." (PMID 40830825, 2025). "Cetuximab (Cmab), a monoclonal antibody that inhibits epidermal growth factor receptor (EGFR), appears to be associated with tumor growth inhibition and is one of the few targeted therapies currently used." (PMID 40917921, 2025). "The results indicated a MSS tumor with EGFR 19del (p.L747_T751del) (VAF: 52.3%), TPR-NTRK1 fusion (VAF: 5.1%), and EGFR amplification (8.5 copies)." (PMID 40843372, 2025). "Compound 17, which exhibited cytotoxicity against PANC−1 cells, was linked to 55 targets, including key targets such as EGFR, AKT1, CDK1, CDK2, MMP9, PIK3CG, and TERT, closely associated with tumour cell proliferation, migration, and apoptosis." (PMID 41006588, 2025). "Tn/STn antigens directly promote tumor progression by activating oncogenic signaling pathways (e.g., EGFR/FAK) and inducing epithelial-mesenchymal transition." (PMID 41383589, 2025). "In vivo, A549 and H358 tumor xenografts that overexpressed BRG1 or had BRG1 silenced were investigated for tumor growth response to EGFR-TKI." (PMID 41514577, 2025). "EGFR upregulation occurs in ~ 66% of HCC cases and has been associated with tumorigenesis, aggressive tumor behavior, metastasis and poor patient survival." (PMID 41040516, 2025). "The average fraction of TILs in EGFR‐amplified tumours was 0.17% ranging between 0 and 0.5%, while the remaining tumours had an average of 12.5% TILs ranging between 0.14 and 27.19%." (PMID 40621643, 2025). "Tumor cells exhibited increased EGFR expression, along with transcriptomic reprogramming characterized by upregulation of signaling, immune, and differentiation pathways, and downregulation of metabolic and protein synthesis genes." (PMID 41307822, 2025). "Research indicates that tumor cells bypass EGFR-TKI suppression by reactivating EGFR and its downstream signaling cascades through various mechanisms." (PMID 40003951, 2025). "Drugs targeting ERBB2, such as EGFR inhibitors, effectively block this signaling pathway, thus inhibiting tumor cell growth and proliferation." (PMID 40170854, 2025). "Studies have confirmed that transfection of lncRNA NEAT1 small interfering RNA (siRNA) to hepatoma cell HepG2, down-regulation of lncRNA NEAT1 expression, can inhibit the expression of EGFR and Bcl-2, thereby inhibiting tumor cell proliferation and invasion." (PMID 41186893, 2025).